ADA (adenosine deaminase)
Diseases named in the same sentence as ADA in open-access papers (continued):
Sharing a sentence is not in itself a finding about the gene and the disease.
preeclampsia (6 papers, 2017 to 2023). Preeclampsia is a hypertensive disorder of pregnancy that is characterized by new-onset hypertension with proteinuria presenting after 20 weeks of gestation, and depending on mild or severe forms may initially present with severe headache, visual disturbances, and hyperreflexia. "ADA supplementation also alleviated symptoms in a mouse model of preeclampsia and growth restriction based on angiotensin II overactivation." (PMID 37367877, 2023). "In vitro studies and animal models have shown that anti-MBG antibodies and ADA-FAB can reverse the NKA inhibitory effect of EDLF in preeclampsia, and anti-MBG antibodies are also effective in reversing vascular fibrosis." (PMID 37628922, 2023). "In a mouse model of preeclampsia induced by the selective deletion of placental adenosine deaminase, adenosine levels markedly and exclusively increased in the placenta." (PMID 37507894, 2023). "Moreover, serum ADA levels were also found to be elevated in inflammatory diseases, such as ectopic pregnancy, gestational diabetes mellitus, preeclampsia, and inflammatory bowel disease." (PMID 36267565, 2022). "Therefore, more studies are necessary to elucidate whether adenosine causes or protects against preeclampsia and to unveil the actual role of ADA in preeclampsia." (PMID 30159340, 2018). "Among the pregnant women, mean of serum ADA was significantly higher in hypertensive and preeclamptic women than in normal pregnant group (p<0.001), indicating a possible decrease in cellular immunity in normal pregnancy and increased preeclampsia cell-mediated immunity." (PMID 29263597, 2017). "Inhibition of NKA in red blood cells (RBC) from patients with preeclampsia is reversed ex vivo by anti-MBG antibodies and ADA-FAB." (PMID 37628922, 2023).
renal failure (6 papers, 2016 to 2024). "A recent publication provides further evidence linking ADA deficiency with renal dysfunction: hemolytic uremic syndrome (HUS) is a common cause of renal failure in young children, and this manifestation is reported in a cohort of ADA-SCID patients." (PMID 27579027, 2016). "Although this would not explain the diagnosis of HUS, it may provide an explanation for the severe renal failure exhibited by ADA-deficient patients, and the subsequently poor clinical response." (PMID 27579027, 2016). "The development of renal failure was also accompanied by an increase of ADA activity that is the enzyme of purine metabolism." (PMID 38402260, 2024). "All challenged animals developed renal failure, characterized by an increase in the creatinine level, total ADA activity and ecto-ADA-1 activity." (PMID 36551818, 2022). "Because, In adult patients with renal failure, haemodialysis is a confounding factor which could reduce the levels of ADA." (PMID 34034670, 2021). "The results indicated that there were statistically significant differences (P< 0.05) between the aging and non-aging groups in terms of HGB, HCT, NEUT#, NEUT%, TP, CHE, UREA, NA, PA, CYSC, ADA, eGFR, APOA, HBDH, HDLC, LDH, TyG, renal insufficiency, and cardiac insufficiency." (PMID 39145313, 2024).
Stroke (6 papers, 2017 to 2025). Sudden impairment of blood flow to a part of the brain due to occlusion or rupture of an artery to the brain. "The immune response enzyme adenosine deaminase (ADA) was significantly associated with higher scores on the National Institutes of Health Stroke Scale (NIHSS) and poorer modified Rankin Scale (mRS) scores at discharge, indicating greater neurological impairment and limited functional recovery." (PMID 41173049, 2025). "Associations between serum ADA activity and presence of stroke." (PMID 36260871, 2022). "In this work, DM was also observed to significantly increase ADA activity in stroke patients." (PMID 36260871, 2022). "Next, we evaluated whether ADA-409-52 provides neuroprotection in vivo in a TE mouse model of stroke." (PMID 33568697, 2021).
viral meningitis (6 papers, 2017 to 2025). Inflammation of the membranes surrounding the brain and spinal cord due to a viral infection. "Adenosine deaminase (ADA) testing in CSF shows 89% sensitivity and 91% specificity of TBM, but ADA levels in bacterial and viral meningitis complicate interpretation due to unclear diagnostic cut-offs." (PMID 39867878, 2024). "The mean levels of ADA were 3.100±2.687 and 3.0024±5.17711 IU/L in bacterial and viral meningitis, respectively (p-value<0.001)." (PMID 39280394, 2024). "CSF ADA results were statistically significantly different between the ‘Viral meningitis/encephalitis’ and ‘Confirmed TBM’ categories." (PMID 28143441, 2017). "Other CSF diagnostic method, such as the Gamma-interferon release assays (IGRAs), requires large CSF volumes (>6 mL), while the Adenosine deaminase (ADA) levels in bacterial and viral meningitis complicate ADA testing interpretation in TBM due to unclear diagnostic cut-offs." (PMID 41181321, 2025).
acute lymphoblastic leukaemia (5 papers, 2010 to 2023). "A trial of cordycepin in combination with the adenosine deaminase inhibitor pentostatin for acute lymphocytic leukaemia issued a preliminary account in 2000, but unfortunately, this study has still not issued a final report." (PMID 34641429, 2021). "Several studies indicate elevation of adenosine deaminase levels in sera of breast, head and neck, colorectal, acute lymphoblastic leukaemia and laryngeal cancers." (PMID 20805891, 2010).
Anxiety (5 papers, 2018 to 2023). Intense feelings of nervousness, tension, or panic often arise in response to interpersonal stresses. "The use of a specific inhibitor of adenosine production, the inhibitor of ecto-5′-nucleotidase (AMPCP/150 mg/kg), and the specific inhibitor of adenosine degradation, the inhibitor of adenosine deaminase, EHNA (100 mg/kg) did not affect the effects over anxiety." (PMID 33082435, 2020).
Arthritis (5 papers, 2021 to 2025). Inflammation of a joint. "There was no statistical correlation between ADA activity and clinical manifestations such as lymphadenopathy, pneumonitis, arthritis, and sore throat." (PMID 35090387, 2022). "In conclusion, the evaluation of ADA, CRP, UA, and RF levels offers significant perspectives on distinguishing between individuals with and without arthritis." (PMID 38699124, 2024).
Ascites (5 papers, 2009 to 2022). Accumulation of fluid in the peritoneal cavity (between the layers of the peritoneum that lines the abdomen). "The ascitic fluid/serum ADA ratio is higher in patients with peritoneal TB than with other causes of ascites." (PMID 19368735, 2009). "After treatment, ADA and NLRP3 of ascites in RG were lower than those before treatment (P < 0.05)." (PMID 36157218, 2022). "In addition, ADA and NLRP3 in RG patients were positively correlated with the disappearance time of abdominal pain and ascites (P < 0.05) and had excellent predictive effect on the adverse reactions during treatment (P < 0.05)." (PMID 36157218, 2022). "What is more, this research also found that ADA and NLRP3 were directly proportional to the disappearance time of abdominal pain and ascites in TP patients, suggesting that the increased levels are directly related to the pathological manifestations of patients." (PMID 36157218, 2022).
glioma (5 papers, 2018 to 2022). A benign or malignant brain and spinal cord tumor that arises from glial cells (astrocytes, oligodendrocytes, ependymal cells). "Recent evidence indicates that ADK and ADA levels are related to glioma progression." (PMID 30441833, 2018). "However, the role of ADAR3, a brain specific high expression adenosine deaminase, in gliomas has rarely been investigated." (PMID 30524204, 2018). "Extracellular adenosine reduced viability in rat glioma cells and ADA reverted this effect." (PMID 30441833, 2018). "ADK and ADA, by regulating adenosine concentration, might also play a role in tumor growth and apoptotic cell death in gliomas, modulating proliferation of glial and endothelial cells." (PMID 30441833, 2018). "ADA and BMP2 expression are correlated with poor prognosis in glioma patients, which were both down‐regulated with the anti‐ETLD1 treatments." (PMID 31863639, 2020). "ADA and ADK levels were upregulated in patients with Grade II and Grade III gliomas compared to control subjects." (PMID 30441833, 2018). "ADA and ADK are upregulated in higher grade gliomas but the relevance for tumor progression requires further research." (PMID 30441833, 2018).
gout (5 papers, 2020 to 2023). A condition characterized by painful swelling of the joints, which is caused by deposition of urate crystals. "In gouty arthritis model mice, Simiao Decoction can effectively reduce the serum UA levels, reduce myeloperoxidase (MPO), XOD, and adenosine deaminase (ADA) activities, and relieve gout-related symptoms such as foot swelling and pain." (PMID 36034697, 2022). "Simiao decoction has the effect of reducing blood uric acid levels, reducing myeloperoxidase (MPO), xanthine oxidase (XOD), adenosine deaminase (ADA) activity, and alleviating gout-related symptoms (such as foot swelling and pain)." (PMID 34721646, 2021). "Considering that both ADA and XOD affect the purine metabolism, we further investigated the enzymatic activation with ADA and XOD in mouse hepatic to explore the exacerbation of gout symptoms by alcohol via purine metabolism." (PMID 37771709, 2023). "Although the reduction of ADA and XOD activity levels is not significant, we have observed that the gout symptoms of mice have been significantly improved." (PMID 35145506, 2022).
heart failure (5 papers, 2014 to 2025). Inability of the heart to pump blood at an adequate rate to meet tissue metabolic requirements. "Adenosine deaminase (ADA), an enzyme that breaks down adenosine and is upstream to XO in the purine degradation pathway, is also observed to have lower activity in heart failure patients." (PMID 39199201, 2024). "The expression of ADA in heart failure has not yet been determined, although it is certain that ADA activity is one of the important factors affecting Ado levels and that it participates in the process of heart failure." (PMID 25170811, 2014).
hepatocellular carcinoma (5 papers, 1978 to 2024). A malignant tumor that arises from hepatocytes. "Adenosine deaminase and adenosine kinase have been measured in rat liver, 12 transplantable hepatomas, regenerating, foetal and neonatal liver, adult and neonatal rat kidney and 2 transplantable kidney tumours." (PMID 207296, 1978). "In rat hepatoma cell lines growing in culture, the toxicity of adenosine correlated inversely with the ratio of adenosine deaminase activity to adenosine kinase activity." (PMID 207296, 1978). "ADA was also reported to play an oncogenic role in hepatocellular carcinoma." (PMID 35586208, 2022).
kidney damage (5 papers, 2021 to 2025). "In this study, higher ADA levels were significantly associated with diabetic nephropathy, neuropathy, and retinopathy, with the strongest correlation observed in nephropathy." (PMID 39493017, 2024). "This suggests that ADA could be a useful biomarker for identifying patients at risk of microvascular complications, particularly nephropathy." (PMID 39493017, 2024). "Higher ADA levels were particularly associated with diabetic nephropathy (p=0.003), while HbA1c levels showed a positive correlation with all three complications: nephropathy, neuropathy, and retinopathy." (PMID 39493017, 2024). "SH-P-1-1 significantly decreased uric acid and creatinine levels, reduced xanthine oxidase and adenosine deaminase activities, alleviated kidney damage, and reduced urate deposition in joints in model rats." (PMID 41487664, 2025).
liver cirrhosis (5 papers, 2021 to 2025). "In previous studies, we also discovered that ADA and NLRP3 were elevated in liver cirrhosis and gastroenteritis, which was associated with the results of this experiment." (PMID 36157218, 2022).
liver disease (5 papers, 2019 to 2025). "Of note, increased ADA activity and/or expression has been observed in several liver disorders, including in patients with metabolic liver disease and inflammatory liver diseases (21, –, 23)." (PMID 40042304, 2025). "The aim of this study was to conduct a cross sectional analysis of liver disease in a cohort of patients with autosomal recessive ADA-SCID." (PMID 37208598, 2023). "We aimed to conduct a cross sectional study to describe liver disease in autosomal recessive ADA-SCID." (PMID 37208598, 2023). "Mice lacking ADA activity (ADA–/–) exhibit many of the metabolic and immune and non-infectious abnormalities observed in ADA-SCID patients including liver disease, skeletal malformations and renal sclerosis." (PMID 30918508, 2019).
ovarian carcinoma (5 papers, 2017 to 2025). A malignant neoplasm originating from the surface ovarian epithelium. "Additionally, CA-125 and ADA were elevated in 12 (100%) cases, indicating significant deviations often linked to ovarian cancer and peritoneal tuberculosis." (PMID 40870860, 2025). "ADA levels were found to be significantly higher in patients with ovarian cancers as compared with benign ovarian tumors." (PMID 29270229, 2017). "ADA has been regarded as a potential biomarker for diagnosis and an agent for the treatment of ovarian cancer." (PMID 29270229, 2017). "ADA overexpression significantly enhanced the expansion, tumor infiltration, and tumor control of CAR-T cells in the both preclinical engineered ovarian carcinoma xenograft model and in vivo CRC model." (PMID 38918817, 2024). "In contrast, ovarian cancer, which can present with similar symptoms, results in significantly higher levels of CA-125 and HE4, and non-TB infections may show increased CA-125 levels but with normal or low HE4, along with negative IGRA and ADA results." (PMID 40870860, 2025).
pericardial effusion (5 papers, 2022 to 2025). Fluid collection within the pericardial sac, usually due to inflammation. "In this patient, ADA levels in the pericardial effusion were elevated; however, PCR testing for Mycobacterium tuberculosis was negative, making tuberculous pericardial effusion unlikely." (PMID 41458507, 2025). "Adenosine deaminase (ADA) level in the pericardial effusion was mildly elevated (42 U/L, reference range, 5.0-20.0); however, no significant causative microbes, including mycobacterium, were detected in cultures of both sputum and the pericardial fluid." (PMID 39872568, 2024).
pulmonary fibrosis (5 papers, 2007 to 2022). Chronic progressive interstitial lung disorder characterized by the replacement of the lung tissue by connective tissue, leading to progressive dyspnea, respiratory failure, or right heart failure. "Results from our study also demonstrate that IL-6 contributes to pulmonary fibrosis in ADA-deficient mice." (PMID 21799929, 2011). "Treating ADA-deficient mice with this antagonist prevented the production of numerous mediators from alveolar macrophages, thus preventing the development of airspace enlargement and pulmonary fibrosis." (PMID 20169073, 2010). "Interestingly, partially adenosine deaminase-deficient mice show upregulation of this receptor and exhibit spontaneous and progressive pulmonary fibrosis and usually die from respiratory distress." (PMID 17534432, 2007). "An animal model showed that adenosine deaminase deficiency might lead to pulmonary fibrosis." (PMID 35681244, 2022). "Genetic loss of CD73 or pharmacological inhibition with a CD73-antibody or by degradation of adenosine with pegylated-adenosine deaminase (PEG-ADA) significantly reduced levels of pro-fibrotic mediators and attenuated the extent of pulmonary fibrosis." (PMID 28836991, 2017).
squamous cell carcinoma (5 papers, 2013 to 2023). A carcinoma arising from squamous epithelial cells. "Squamous cell carcinoma of the tongue exhibits a gradual rise in salivaryadenosine deaminase (ADA) activity from stage I to stage III." (PMID 37693919, 2022). "Salivary adenosine deaminase (ADA) activity is significantly increased in squamous cell carcinoma of the tongue progressively from stage I to stage III." (PMID 24616813, 2014). "In addition, the serum ADA levels were seen to increase significantly with the progression of squamous cell carcinoma of the tongue from stage I to stage III." (PMID 37958429, 2023).
Thrombocytopenia (5 papers, 2021 to 2024). A reduction in the number of circulating thrombocytes. "Features associated with hMPE included pleural ADA ≥ 150 IU/L, PMN < 50%, thrombocytopenia, and high serum LD." (PMID 38178065, 2024). "In our study, features associated with TBP were pleural ADA between 70 and 150 IU/L (inversely, negative association with ADA ≥ 150), lymphocytes ≥ 35%, eosinophils < 10%, LD/ADA ratio < 18, absence of leukocytosis, and absence of thrombocytopenia." (PMID 38178065, 2024).
type 1 diabetes (5 papers, 2009 to 2025). "A reduction in AdA formation has been described in type 1-diabetes." (PMID 27764229, 2016). "Despite earlier evidence indicating a high prevalence of thyroid autoimmunity in individuals with type 1 diabetes, screening was performed at irregular intervals, reflecting the lack of specific ADA recommendations in the late 1980s and early 1990s." (PMID 41255538, 2025).
celiac disease (4 papers, 2013 to 2023). An autoimmune genetic disorder with an unknown pattern of inheritance that primarily affects the digestive tract. "Adenosine deaminase (ADA), a cytoplasmic enzyme that is involved in the catabolism of purine bases, is elevated in celiac disease, and is therefore a useful diagnostic marker." (PMID 24678255, 2013). "Myeloperoxidase (MPO) activity, adenosine deaminase, nitric oxide (NOx), thiobarbituric acid, catalase (CAT), superoxide dismutase (SOD), glutathione peroxidase (GPx), and DNA damage were evaluated in peripheral blood samples from 47 celiac disease patients and 31 controls." (PMID 32555942, 2020).
co-infection (4 papers, 2012 to 2025). "Previous studies have also revealed that ADA–MP coinfection was associated with severe community-acquired pneumonia in children." (PMID 41012693, 2025). "More involvement of monocytemacrophage system in the HIV co-infection compared to the mono-infection is the main cause of higher ADA activity in co-infected patients since this system participates in the immune responses and regulates the exact amounts of adenosine in the immune cells." (PMID 37942194, 2023). "It is well established that co-infection of HIV with HBV increases the ADA activity much more than the mono-infection with HIV or HBV." (PMID 37942194, 2023). "Therefore, since the increase in the enzyme activity occurs in the early stages of the disease process, some studies have suggested that elevated ADA activity should be considered as a potent marker for the detection of HIV-HBV co-infection." (PMID 37942194, 2023). "In this regard, serum adenosine deaminase activity (ADA), FibroTests, AST-to-Platelet Ratio Index (APRI), Fibrosis-4, Hyaluronic acid, and micro ribonucleic acids (MiR) have been investigated as potential biomarkers for diagnosis of HIV-HCV/HBV co-infections." (PMID 37942194, 2023). "Therefore, the optimal cutoff values for ADA are still a matter of debate, which may be attributed to variations in disease prevalence rates, sample sizes, different test methods, or the presence of HIV co-infection." (PMID 37940883, 2023). "Host immune factors provide greater diagnostic accuracy, including levels of IFN-γ and Adenosine Deaminase (ADA), both of which have >95% specificity and sensitivity, appear to be unaffected by HIV co-infection and do not require any sample preparation." (PMID 22295081, 2012).
colorectal cancer (4 papers, 2020 to 2024). A primary or metastatic malignant neoplasm that affects the colon or rectum. "The genes that showed the highest variability (more than two-fold) in colorectal cancer included HPRT and ADA." (PMID 33457124, 2020).